IL1RN (interleukin 1 receptor antagonist)
Diseases named in the same sentence as IL1RN in open-access papers (continued):
Sharing a sentence is not in itself a finding about the gene and the disease.
cryptococcosis (1 paper, 2025). An acute or chronic, localized or disseminated infection by Cryptococcus neoformans. "Since IL-1β levels and the expression of its receptor (Il1rn) are high in H99-infected brains, it is probable that reduction in Lcn2 antagonizes the effects of this pro-inflammatory cytokine and serves as a protective mechanism to mitigate brain tissue damage during cryptococcosis." (PMID 40038673, 2025).
dementia (1 paper, 2020). Loss of intellectual abilities interfering with an individual's social and occupational functions. "A study analyzing elderly participants in the Cardiovascular Health Study showed that rs17042917 and rs4251961 variants of the IL1RN gene were associated with the baseline cognitive status, supporting the proinflammatory cytokine IL-1 as a biomarker of dementia status." (PMID 33352859, 2020).
dengue (1 paper, 2019). "Elevated levels of anti-inflammatory cytokine IL1RN/IL1Ra was previously observed in dengue patients and IL1RN/IL1Ra level was higher in dengue with the warning signs patients compared to the dengue without the warning signs patients." (PMID 30744623, 2019).
diarrhoea (1 paper, 2022). "Some of the DEGs in diarrhoea-susceptible sheep, enriched in GO terms and sub-network analysis, included IL-6, LOC101121216 (serum amyloid A), SIGLEC1, CHI3L1, S100A9, CD14, CD68, CD86, Ovar-DRB1, IL1RL1, LOC101103238 (CXCL5), CCL22 and IL1RN." (PMID 35576023, 2022).
duodenal ulcer (1 paper, 2013). An ulcer in the duodenal wall. "Interleukin-1β (IL1β) and interleukin-1 receptor antagonist (IL1RN) gene polymorphisms have been found to be associated with increased risk of AG, GC and duodenal ulcer (DU), but contradictory results have been reported." (PMID 27785255, 2013).
Encephalopathy (1 paper, 2025). Encephalopathy is a term that means brain disease, damage, or malfunction. "Specifically, the haplotype RN2 of IL1RN, which leads to decreased IL-1Ra production, carried a higher risk of encephalopathy." (PMID 40310164, 2025).
epilepsy (1 paper, 2024). A brain disorder characterized by episodes of abnormally increased neuronal discharge resulting in transient episodes of sensory or motor neurological dysfunction, or psychic dysfunction. "For example, mutations in the gene encoding for interleukin-1 receptor antagonist (IL1RN) can cause a rare form of epilepsy called deficiency of IL1RN, which is characterized by recurrent febrile seizures, systemic inflammation, and skin lesions." (PMID 38612542, 2024).
esophageal cancer (1 paper, 2026). A primary or metastatic malignant neoplasm involving the esophagus. "Further in vitro experiments demonstrated that silencing IL1RN and IL36G in macrophages markedly suppressed the malignant phenotypes of esophageal cancer cells." (PMID 41704537, 2026).
Fever (1 paper, 2023). Body temperature elevated above the normal range. "The high induction of IL1RN in mutant-infected but not in WT-infected cells could be the main contribution to the lack of fever observed in the mutant-infected pigs." (PMID 37513744, 2023).
gallbladder cancer (1 paper, 2016). "Multiple polymorphisms in genesassociated with the immune system, inflammation, and oxidative stress that have been linkedto the development of gallbladder cancer like PTGS2, TLR2, TLR4, IL1RN, IL10, IL8, CCR5,LXRB, and OGG1." (PMID 28105075, 2016).
gastric adenocarcinoma (1 paper, 2024). "The interleukin-1B gene (IL-1B), interleukin-1 receptor antagonist gene (IL-1RN), and PPARγ Pro12Ala polymorphism act in HP-associated gastric adenocarcinoma." (PMID 38357448, 2024).
glaucoma (1 paper, 2024). Increased pressure in the eyeball due to obstruction of the outflow of aqueous humor. "Our findings revealed a significant decrease in the mRNA levels of SA1009 and MMP3 in the glaucoma model group compared to the normal group, while SERPINA3, IL1RN, and LCN2 expression increased." (PMID 39125762, 2024). "Our study identified and validated six neuroinflammation-related hub genes in glaucoma (SERPINA3, LCN2, MMP3, S100A9, IL1RN, and HP)." (PMID 39125762, 2024).
glioblastoma (1 paper, 2020). The most malignant astrocytic tumor (WHO grade IV). "An experimental study of human glioblastoma cells showed that IL1RN secreted by tumor cells can counteract IL-1 function, which represents a potential escape mechanism that supports cancer growth." (PMID 33238942, 2020).
Granuloma (1 paper, 2025). A compact, organized collection of mature mononuclear phagocytes, which may be but is not necessarily accompanied by accessory features such as necrosis. "Our spatial transcriptomics data provide gene expression patterns at single-cell resolution within cryptococcal granulomas and reveal highly heterogenous myeloid cells in the granuloma center, some of which appear highly interferon-responsive based on expression of Il1rn, Nos2 and Acod1." (PMID 40568097, 2025).
Graves ophthalmopathy (1 paper, 2024). An autoimmune disorder of the EYE, occurring in patients with Graves disease. "The IL1RN production has also been reported to increase in response to low doses of either UV or ionizing irradiation in cultured human orbital fibroblasts derived from patients with active Graves’ ophthalmopathy." (PMID 39201290, 2024).
Hashimoto thyroiditis (1 paper, 2022). An autoimmune disorder caused by the production of autoantibodies against thyroid tissue. "Polymorphisms on IL1RN have been found to be associated with the occurrence of Hashimoto’s thyroiditis and to predict severity." (PMID 35053465, 2022).
hepatotoxicity (1 paper, 2018). Toxicity that causes injury to the liver or impairs the liver function. "However, IL-1RN 1/3 genotype and allele 3 were overrepresented in HIV-infected individuals with hepatotoxicity compared with healthy controls (5.9% versus 2.0%, OR = 2.39, 95% CI: 0.37–15.33, P = 0.69 and 2.94% versus 1.64%, OR = 1.62, 95% CI: 0.20–8.57, P = 0.93, resp)." (PMID 29849489, 2018).
Hyperglycemia (1 paper, 2021). An increased concentration of glucose in the blood. "Overexpression of IL1RN increased the mean serum level of IL1RA after temporary xenotransplantation, with a significant reduction of hyperglycemia." (PMID 34576149, 2021).
hyperlipidemia (1 paper, 2025). "In case of liver inflammation related genes (IL-1β, TNF-α, IL-6, IL-18, CCL20, and NF-κB) their expression levels were significantly (P < 0.05) upregulated and IL-1RN was significantly (P < 0.05) downregulated in the liver of hyperlipidemia group." (PMID 41144456, 2025).
hyperuricemia (1 paper, 2025). An abnormally high level of uric acid. "Loci contributing most strongly to the non-hyperuricemia causal effect included three genes: IL1R1, IL1RN, and SLC30A5." (PMID 40385401, 2025).
IgA nephropathy (1 paper, 2017). "For example, previous study showed that the haplotype of IL1B, IL1RN, IL1R1, and IL1R2 increased the risk of venous thrombosis, and IL1/IL1Ra, CTLA-4 and Apo1/Fas genes polymorphisms associate with IgA nephropathy." (PMID 28881593, 2017).
keloid (1 paper, 2023). An irregularly shaped, elevated mark on the skin caused by deposits of excessive amounts of collagen during wound healing. "Five hub genes were linked to keloid recurrence, including CHI3L1, IL1RN, MMP7, TNFAIP3, and TNFAIP6." (PMID 37685578, 2023). "As the upregulation of IL-6 plays a role in keloid scars, we infer that IL1RN participates in the deposition of collagen via IL-6 signalling pathways." (PMID 37685578, 2023). "The mechanism of IL1RN in the recurrence of keloid needs more explorative research." (PMID 37685578, 2023). "In the present study, the hub genes (CHI3L1, IL1RN, MMP7, TNFAIP3, and TNFAIP6) were mainly involved in the regulation of inflammatory response, IL-17 signalling pathway, and TNF signalling pathway, which is consistent with previous findings in keloids." (PMID 37685578, 2023). "The qRT-PCR experiment was used for detecting the differential expression of five hub genes (CHI3L1, IL1RN, MMP7, TNFAIP3, and TNFAIP6) in recurrent and non-recurrent keloid tissues." (PMID 37685578, 2023).
lichen sclerosus (1 paper, 2022). "However, there is almost no data reflecting the expression of cytokines genes in the LS tissue what prompted us to determine the mRNA levels of IL-1A, IL-6, IL-1B, IL-1RN, TGF-β1 and INF-γ genes in a large sample of penile lichen sclerosus tissue as compared to control penile tissues." (PMID 35103930, 2022).
liver cancer (1 paper, 2023). An epithelial or non-epithelial malignant neoplasm that arises from the liver. "The results showed that the expression of PAIP1 had a significant negative correlation (P < 0.05) with that of APOC3, CCL14, IL1RN, SERPINA3, and HAMP in liver cancer tissues." (PMID 37101794, 2023).
lumbar disc herniation (1 paper, 2014). "Actually, IL1B polymorphisms have previously been associated with symptomatic lumbar disc herniation, and together with IL1RN polymorphism associated with low back pain in the general population." (PMID 25207923, 2014). "The analysis of clinical outcome over time, i.e. from inclusion to 12 months, revealed that the progression of pain and disability after lumbar disc herniation may be associated with the IL1A/IL1RN genotype." (PMID 25207923, 2014). "The combination of IL1A rs1800587 T allele and IL1RN rs2234677 A allele may increase the risk of a chronic outcome and persistent pain following lumbar disc herniation." (PMID 25207923, 2014).
lymphopenia (1 paper, 2022). Reduction in the number of lymphocytes. "For examples, monocyte alterations (CD74, CIITA mRNA), lymphopenia (CD3, IL7R mRNA), increased anti-inflammatory response (IL10, IL1RN mRNA), altered IFN response (OAS2, IFNG mRNA) were observed." (PMID 36389738, 2022).
male infertility (1 paper, 2012). The inability of the male to effect fertilization of an ovum after a specified period of unprotected intercourse. "In the present study we have examined the association of Variable Number Tandem Repeats (VNTR) polymorphism of the Interleukin-1 receptor antagonist gene (IL1RN) with human male infertility." (PMID 23251650, 2012). "Another evidence from IL1RN knockout mouse model shows that the knockout mice have higher levels of IL-1 in the testis and the IL1RN-deficiency leads to male infertility in these mice due to impaired ability of sperm to fertilize oocyte." (PMID 23251650, 2012). "Based on the biological and pathologic importance of (VNTR) polymorphism of the human IL1RN, it is possible that variations in the IL1RN gene may contribute to the clinical outcomes of male infertility." (PMID 23251650, 2012).
middle cerebral artery infarction (1 paper, 2023). Necrosis occurring in the middle cerebral artery distribution system which brings blood to the entire lateral aspects of each cerebral hemisphere. "Moreover, CASP3, CASP6, as well as GOT1 and IL1RN, have been implicated in vascular dementia, middle cerebral artery infarction and transient cerebral ischemia (FDR = 0.041)." (PMID 38107644, 2023).
myopia (1 paper, 2025). "Polymorphisms in IL1β (rs1143627) and IL1RN (rs315952) were associated with high myopia, supporting the role of dysregulated cytokine signaling." (PMID 41138034, 2025).
nasal polyps (1 paper, 2022). "Polymorphisms in the IL-1 receptor antagonist gene (IL1RN) are associated with CRS, and in CF, elevated IL-1β is associated with the presence of nasal polyps (41, –, 44)." (PMID 36094193, 2022).
non-alcoholic fatty liver disease (1 paper, 2024). "Additionally, one study examining genes related to metabolic risk factors in non-alcoholic fatty liver disease and HCC reported that IL1RN is a protective prognostic gene for HCC." (PMID 39445019, 2024).
non-bacterial osteomyelitis (1 paper, 2014). "Although the etiology of chronic non-bacterial osteomyelitis is still unknown, deficiency of IL-1β receptor antagonist and neonatal-onset multisystem inflammatory disease are caused by mutations in the IL1RN and NLRP3 genes, respectively, and result in over-activation of the IL-1β pathway." (PMID 24973754, 2014).
osteophytes (1 paper, 2016). "NCOR2 and CD36 genes were associated with induction of radiographic knee OA measured as either a K/L grading of ≥2.0 or the presence of osteophytes, while the polymorphisms at CILP, TNA, IL1RN and variation at inflmmatory genes appeared to correlate with radiographic progression over time." (PMID 27457563, 2016).
osteoporosis (1 paper, 2025). A condition of reduced bone mass, with decreased cortical thickness and a decrease in the number and size of the trabeculae of cancellous bone (but normal chemical composition), resulting in increased fracture incidence. "Genetic factors associated with osteoporosis susceptibility in the Chinese Han population have been identified, including rs10490571, rs956730, and rs3917225 in IL-1R1 and rs17042888 in IL-1RN." (PMID 40153574, 2025). "Beyond its implications in osteoporosis, IL1RN has shown promise in AD research." (PMID 40153574, 2025). "Consequently, IL1RN has been identified as a novel therapeutic target for osteoporosis." (PMID 40153574, 2025).
osteosarcoma (1 paper, 2025). A usually aggressive malignant bone-forming mesenchymal neoplasm, predominantly affecting adolescents and young adults. "The LbdCpf1-p300 construct was successfully employed to concurrently stimulate the expression of MYOD, a transcription factor linked to myogenic differentiation, and IL1RN, an interleukin-1 receptor antagonist, in U2OS (human osteosarcoma) and MCF7 cells." (PMID 40650152, 2025).
pancreatic adenocarcinoma (1 paper, 2020). "The results showed that increased IL1RN expression levels were significantly associated with shorter OS in kidney renal clear cell carcinoma (KIRC), brain lower grade glioma (LGG), pancreatic adenocarcinoma (PADD) and uterine corpus endometrial carcinoma (UCEC)." (PMID 33238942, 2020).
papillary thyroid carcinoma (1 paper, 2020). "However, the biological function of IL1RN in papillary thyroid carcinoma (PTC) remains undetermined." (PMID 33238942, 2020).
prion disease (1 paper, 2017). A transmissible disease that is caused by a protein that is able to induce abnormal folding of normal cellular proteins, leading to characteristic spongiform brain changes, which are associated with neuronal loss without an inflammatory response. "We also validated the upregulation of IL1RN by Meth, which could contribute to controlling astrocytosis, as suggested in the prion disease model." (PMID 28279172, 2017).
prostate adenocarcinoma (1 paper, 2020). "After analyzing human prostate adenocarcinomas in The Cancer Genome Atlas (TCGA) Program, the IL1RN was indeed tightly correlated with both CCL2 and CXCL1." (PMID 33322099, 2020).
pustular psoriasis (1 paper, 2023). "Other genes involved in pustular psoriasis are SERPINA1 and SERPINA3 (serine protease inhibitors that inhibit cathepsin G, neutrophil elastase, and proteinase 3), TNIP1 and IL1RN." (PMID 37628670, 2023).
sarcoidosis (1 paper, 2025). Sarcoidosis is a multisystemic disorder of unknown cause characterized by the formation of immune granulomas in involved organs. "IL1RN has been implicated in sarcoidosis through its role in modulating inflammatory responses by antagonizing IL-140." (PMID 40075078, 2025). "Among 19 protein-sarcoidosis associations, strong genetic colocalization evidence was observed for 8 pairs, including BTN3A3, ANXA11, ITPKA, BTN3A1, G3BP1, IL1RN, IL2RB, and NFKB1." (PMID 40075078, 2025).
Sciatica (1 paper, 2021). Pain in the lower back and hip radiating in the distribution of the sciatic nerve. "The PPI network suggested that TLR4, MMP9, MPO, CAMP, RETN, TLR5, and IL1RN were key genes in the dysregulation of genes in the peripheral blood of patients with sciatica." (PMID 33573686, 2021). "Bioinformatic analysis revealed that most of the DEGs-baseline were related to immunity and the inflammatory response and that TLR4, MMP9, MPO, CAMP, RETN, TLR5, and IL1RN were key genes involved in the dysregulation of genes in the peripheral blood of patients with sciatica." (PMID 33573686, 2021). "We also found that TLR5, IL1RN, and SLC8A1 were upregulated in sciatica patients at baseline compared with healthy controls and downregulated after integrated TCM treatment compared with baseline, indicating that these genes played an important role in the pathogenesis and remission of sciatica." (PMID 33573686, 2021).
septic arthritis (1 paper, 2024). "In our previous discovery proteomics study, interleukin 1 receptor antagonist protein (IL1RN) was identified as being upregulated in the synovial fluid of horses with septic arthritis compared to horses post eradication of joint infection and horses with experimentally induced non-septic synovitis." (PMID 39057983, 2024).
Shock (1 paper, 2021). The state in which profound and widespread reduction of effective tissue perfusion leads first to reversible, and then if prolonged, to irreversible cellular injury. "When constructing the signaling network for SOFA criterion 3, reflecting circulatory failure, upregulated IL1RN was identified as directly involved in hypotension and septic shock and in the production of lactic acid, indicating tissue hypoperfusion." (PMID 34573990, 2021).
skin carcinoma (1 paper, 2020). "Thus, similar to the tumor-promoting effect of inflammation as demonstrated by TNFα in skin carcinoma model, tumor cells may eventually escape the immune system by reducing the IL1RN level in the tumor microenvironment and develop into malignant cancer in late stages." (PMID 32244522, 2020).
skin infection (1 paper, 2024). An inflammatory process affecting the skin, caused by bacteria, viruses, parasites, or fungi. "Since neutrophils followed by macrophages highly expressed Il1rn, we examined if IL-1Ra produced by neutrophils and macrophages play a role in host defense against C. auris skin infection." (PMID 39536069, 2024).
skin inflammation (1 paper, 2024). "Since IL-10 and IL-1rn are key anti-inflammatory cytokines that regulate tissue inflammation, an acute dermatitis model was employed." (PMID 39594490, 2024). "Consequently, this result proves that A06, B03, and B05, identified as MsrB1 inhibitors, suppress the expression of IL-10 and IL-1rn and, thereby, promote skin inflammation." (PMID 39594490, 2024).
sleeping sickness (1 paper, 2019). "This study revealed that one SNP rs1800794 of IL1A and one VNTR rs2234663 of IL1RN were associated with the increased risk to be infected by Trypanosoma brucei gambiense and develop sleeping sickness in southern Cameroon." (PMID 30908482, 2019). "Results of this study have shown that the genotype (TT) and minor allele (T) of IL1A gene and the genotype 1A3A VNTR of IL1RN are associated with an increased risk of getting T. b. gambiense infections and develop sleeping sickness in major ethno-linguistic groups of the Cameroonian population." (PMID 30908482, 2019). "This study revealed that one SNP (rs1800794) of IL1A and one VNTR (rs2234663) of IL1RN were associated with an increased risk to be infected by T. b. gambiense and develop HAT in inhabitants of sleeping sickness foci of southern Cameroon." (PMID 30908482, 2019). "The minor allele T and the genotype TT of SNP rs1800794 in IL1A as well as the genotype 1A3A of IL1RN rs2234663 VNTR seem to increase the risk of getting Trypanosoma brucei gambiense infections and develop sleeping sickness in southern Cameroon." (PMID 30908482, 2019).
status epilepticus (1 paper, 2023). Status epilepticus is defined as a continuous seizure lasting more than 30 min, or two or more seizures without full recovery of consciousness between any of them. "Furthermore, we observed that, when exposing the animals to more Il1b by silencing its endogenous antagonist Il1rn, there was a better response to status epilepticus with decreased animal mortality in the acute phase of the PILO model." (PMID 35061107, 2023).